HDAC3 (histone deacetylase 3)
Diseases named in the same sentence as HDAC3 in open-access papers (continued):
Sharing a sentence is not in itself a finding about the gene and the disease.
Cognitive impairment (12 papers, 2015 to 2025). Abnormal cognition is characterized by deficits in thinking, reasoning, or remembering. "Last, it has been well known that BBB leakage in T2DM may lead to cognitive impairment, which was not examined in the present study; however, the role and mechanism of HDAC3 inhibition in the BBB-associated neurological complication such as cognitive impairment warrant further investigation." (PMID 31101061, 2019). "Although deletion or selective inhibition of HDAC3 has been proposed as a promising intervention to improve memory and neural plasticity, the presence of severe cytotoxicity and cognitive impairment in Hdac3‐deleted mice challenged its therapeutic effect." (PMID 37721401, 2024). "Our data indicate that melatonin treatment attenuates CRSD‐induced cognitive impairment via regulating HDAC3‐Bmal1/Clock interaction." (PMID 37721401, 2024). "Melatonin treatment attenuates CRSD‐induced cognitive impairment via regulating HDAC3‐Bmal1/Clock interaction." (PMID 37721401, 2024). "Wood’s group identified HDAC3 as a negative regulator of long-term memory formation, and demonstrated HDAC3 inhibition was able to improve cognitive impairments." (PMID 28106794, 2017). "Our results and those of Thomas and colleagues indicate that early targeting with an HDAC3-selective inhibitor significantly prevents or delays cognitive deficits, somatic CAG repeat expansions and motor dysfunction in HD mice." (PMID 28729730, 2017). "This study tested the idea that HDAC3 is important in HD pathology via its transcriptional repressive effects contributing to cognitive impairment and in fueling somatic CAG repeat expansions." (PMID 28729730, 2017). "Interestingly, pretreatment with melatonin was found to ameliorate CRSD‐induced cognitive impairment as well as HDAC3 and Bmal1/Clock interruption in this study." (PMID 37721401, 2024). "In summary, our results highlight the role of HDAC3 activity in the age related cognitive deficits." (PMID 26577291, 2015). "One study using a six-beam simplified GCRsim found that pharmacological HDAC3 inhibition reversed LTP deficits and restored behavioral performance, indicating that epigenetic modulation can mitigate GCR-induced cognitive impairments." (PMID 41008589, 2025). "Chronic melatonin pretreatment reverses the interruption of HDAC3 and circadian rhythms from CRSD, which eventually ameliorates cognitive deficits." (PMID 37721401, 2024). "The upregulation of HDAC2 and HDAC3 has been observed in the hippocampus of offspring exposed to sevoflurane during late pregnancy on PND 1 and PND 35 accompanied with long‐term cognitive impairment." (PMID 37073496, 2023).
glioblastoma (12 papers, 2017 to 2025). The most malignant astrocytic tumor (WHO grade IV). "Based on the function of HDAC3 in glioblastoma, it has been considered a potential therapy molecular to conquer the drug resistance of glioblastoma." (PMID 39068393, 2024). "Other studies have shown that saffron extracts decrease HDAC1 and HDAC3 expression in glioblastoma cell lines under treatment with saffron extracts in a dose-dependent manner." (PMID 38201944, 2023). "HDAC-3 overexpression has been shown in glioblastoma (grade IV by definition) and poorly differentiated hepatocellular, prostate, serous subtype of endometrial and ovarian and urothelial bladder carcinoma." (PMID 33799478, 2021). "Similarly, HDAC3 also takes effect in the chemoresistance of hypoxic glioblastoma." (PMID 39068393, 2024). "It is indicated that HDAC4 has a better prognosis, while, accordingly, HAT1, HDAC1, HDAC3 and HDAC7 may have a poor prognosis for glioblastoma." (PMID 39068393, 2024). "Furthermore, five histone acetylation regulators were selected to be considered as the significant glioblastoma prognosis genes, in which HDAC1, HDAC3, HDAC4 and HDAC7 belong to histone deacetylases differently, HAT1 is a histone acetylase." (PMID 39068393, 2024). "Moreover, upon JUN, CEBPB and HDAC3 knockdown, the expression levels of MGMT decreased significantly, suggesting that these genes could regulate drug resistance of glioblastoma by mediating MGMT status." (PMID 30775317, 2019).
Stroke (12 papers, 2016 to 2026). Sudden impairment of blood flow to a part of the brain due to occlusion or rupture of an artery to the brain. "Beyond the actions of individual enzymes, the broader regulatory networks involving p300 and HDAC3 are intimately linked to the clinical manifestations of stroke recovery." (PMID 41585085, 2025). "It appeared that HDAC3-deficient microglia orchestrated the cell composition of the post-stroke brain by recruiting more macrophage reinforcements to the infarct core." (PMID 39744685, 2025). "Correspondingly, depleting microglial HDAC3 further elevated the expression of numerous stroke-induced upregulated genes associated with leukocyte chemotaxis." (PMID 39744685, 2025). "HDAC3-regulated PGE2 production by microglia constitutes phobic anxiety susceptibility after stroke and a protective approach of gamma visual stimulation can be a candidate new therapy." (PMID 35251047, 2022). "Given that HDAC3 connects stroke and emotion regulation, it is easy to think whether HDAC3 mediates anxiety susceptibility after stroke." (PMID 35251047, 2022). "Therefore, it is reasonable that the early-stage HDAC3-deficient microglia may have exerted determinant effects on the stroke-induced white matter injury." (PMID 39744685, 2025). "Therefore, our result indicated that HDAC3-deficient microglia may also directly contribute to the reduced myelin damage after stroke." (PMID 39744685, 2025). "Collectively, HDAC3-miKO promoted oligodendrogenesis of the post-stroke brain and restored structural and functional integrity of white matter long-term after tFCI." (PMID 39744685, 2025). "Collectively, these findings position HDAC3 as a central regulator of lactylation homeostasis, with significant implications for neuronal survival, inflammation, and tissue recovery following stroke and other pathological insults." (PMID 41585085, 2025). "HDAC3 expression increases during early phases of experimental stroke, contributing to neurotoxicity, as described in the second and third sections." (PMID 40867911, 2025). "In this case, we isolated CD45intCD11b+ microglia on day 3 after tFCI and performed bulk RNA-seq to investigate the mechanism by which HDAC3-miKO modulated post-stroke white matter." (PMID 39744685, 2025). "Our recent findings have preliminarily revealed a potential link between microglial HDAC3 and white matter injury following stroke." (PMID 39744685, 2025). "We have previously shown that selective inhibition of histone deacetylase 3 (HDAC3) decreases infarct volume and improves long-term functional outcomes after stroke." (PMID 36258136, 2023). "Our data support that selective inhibition of HDAC3 regulates neuroinflammation after experimental stroke." (PMID 36258136, 2023). "We have previously shown that selective inhibition of HDAC3 decreases infarct volume and improves long-term functional outcomes after stroke." (PMID 36258136, 2023). "Collectively, these results demonstrate that the inhibition of HDAC3 preconditions the brain against ischemic insults, indicating a new approach to evoke endogenous protection against stroke." (PMID 27965534, 2016). "Histone deacetylase 3 (HDAC3) has emerged as a pivotal “eraser” enzyme capable of removing lactylation modifications from proteins, thus playing a crucial role in regulating the homeostasis of protein lactylation after stroke." (PMID 41585085, 2025). "Indeed, HDAC3-miKO promoted post-stroke oligodendrogenesis and long-term histological and functional integrity of white matter." (PMID 39744685, 2025).
Stroke (continued). "Future studies should include both male and female mice to better understand the role of HDAC3 in stroke and how sex might influence the outcomes." (PMID 39744685, 2025). "While our previous study has preliminarily indicated the potential role of HDAC3-miKO in white matter injury by MBP/SMI32 immunostaining 30, further investigation is still needed to determine how exactly HDAC3-miKO exerts its role in post-stroke white matter, either protective or reparative." (PMID 39744685, 2025). "In summary, the pharmacological manipulation of lactylation via p300 inhibitors and HDAC3 activators represents a promising avenue for the mitigation of post-stroke injury and fatigue, with preclinical data supporting their efficacy and laying the groundwork for future translational studies." (PMID 41585085, 2025). "In this way, we inferred that the reduction of this contact induced by HDAC3-miKO may protect intact myelin fibers from secondary injury following stroke." (PMID 39744685, 2025). "Furthermore, we highlight lactylation-related enzymes, including p300 and HDAC3, as potential therapeutic targets, and discuss emerging biomarkers for monitoring lactylation dynamics in stroke patients." (PMID 41585085, 2025). "Indeed, our further investigation revealed that deletion of microglial HDAC3 decreased the SMI32/MBP ratio 35 days after stroke, which was highly correlated with the ameliorated sensorimotor behavioral outcomes." (PMID 39744685, 2025). "The study also preliminarily uncovered that HDAC3-miKO decreased the MBP/SMI32 ratio 35 days after tFCI 30, leading us to further question how HDAC3 was implicated in the de-/re-myelination process after stroke." (PMID 39744685, 2025). "Previous studies also showed that HDAC3 inhibition had neuroprotective effects in stroke." (PMID 32098619, 2020). "Inhibition or genetic manipulation that disrupts HDAC3-mediated delactylation leads to aggravated neuronal injury and larger infarct volumes, underscoring the enzyme’s importance in maintaining lactylation-mediated protective responses in the post-stroke brain." (PMID 41585085, 2025). "Since HDAC3-miKO promoted oligodendrogenesis and improved white matter repair, we hypothesized that these extra macrophages may be involved in stroke-induced myelin debris removal considering that phagocytosis of tissue debris is one of the core functions of macrophages." (PMID 39744685, 2025). "Therefore, our findings reveal role of the HDAC3/Cox1/EP2 signalling network in susceptibility to poststroke anxiety and suggest that gamma oscillation can be a useful therapy in alleviating susceptibility to additional stress exposure after stroke." (PMID 35251047, 2022). "Adult male Wistar rats were subjected to 2-h middle cerebral artery occlusion (MCAO) and randomly treated i.p. with either vehicle or a selective HDAC3 inhibitor (RGFP966) at 2 and 24 h after stroke." (PMID 36258136, 2023). "In this study, we demonstrated that HDAC3-miKO played a reparative but not protective role in post-stroke white matter." (PMID 39744685, 2025). "Microglia-specific deletion or pharmacological inhibition of HDAC3 reduces expression of TNF α, IL 1β, IL 6, and iNOS, represses NF-κB targets, shifts the microglial phenotype toward an anti-inflammatory state, and improves stroke outcomes." (PMID 40867911, 2025). "In the context of stroke, while BBB disruption has served as a prerequisite for macrophages infiltration, we believed that HDAC3-miKO did not aggravate BBB breakdown after stroke, given the unchanged number of other infiltrated immune cells." (PMID 39744685, 2025). "Notably, experimental models have shown that HDAC3, HDAC6, and HDAC11 exhibit increased expression in the early stages following ischemic insult, suggesting their contribution to the pathophysiology of stroke." (PMID 40867911, 2025).
Stroke (continued). "Whether HDAC3 contributes to the progression of phobic anxiety under stroke stress has not been reported." (PMID 35251047, 2022). "However, since sex differences in ischemic stroke are well-documented 62, our exclusion of females means we did not examine the potential role of microglial HDAC3 in females, nor did we investigate possible sex-specific effects on stroke recovery and immune responses." (PMID 39744685, 2025).
ischemic stroke (11 papers, 2019 to 2025). A stroke disorder caused by obstruction of blood flow to the brain, due to thrombotic (local blood clot formation) or embolic (due to a blood clot or other material traveling from another site) event. "The overexpression of microglial PU.1 in an AAV vector successfully reversed the protective effect of HDAC3 knockout on ischemic stroke, demonstrating the key pathological role of the HDAC3/PU.1 axis in the pathogenesis of this condition." (PMID 41012511, 2025). "After an ischemic stroke, HDAC3 regulates the nuclear localization and acetylation of microglial p65, which enhances the activation of the cGAS-STING pathway and transcriptionally promotes the production of cGAS." (PMID 39649720, 2024). "Ischemic stroke induces upregulation of HDAC3 in the peri-infarct area." (PMID 36258136, 2023). "The upregulation of HDAC3 in ischemic stroke mediates deleterious effects; specific inhibition of HDAC3 protects the brain against ischemic injury 24 hours after MCAO by initiating a series of gene expression programs associated with neuroprotection in animal models." (PMID 30906786, 2019). "In this study, we aimed to explore the protective effect of PTS against neurological deficits and secondary injury against ischaemic stroke through histone deacetylase 3 (HDAC3)/Nrf1-mediated microglial actions, which might facilitate further translational studies." (PMID 39198723, 2024). "The HDAC3–p65–cGAS–STING pathway in microglia plays a crucial role in neuroinflammation and tissue injury induced by ischaemic stroke." (PMID 39198723, 2024). "The current study provides evidence that early administration of a selective HDAC3 inhibitor (RGFP966) in vivo decreases cerebral edema and BBB leakage after ischemic stroke." (PMID 36258136, 2023). "Therefore, the HDAC3-p65-cGAS-STING pathway may be a therapeutic target for ischemic stroke." (PMID 32863951, 2020). "Additionally, our previous study revealed that a selective inhibitor of histone deacetylase 3 (HDAC3) alleviated the inflammatory response and protected against ischemic stroke by suppressing the activation of the AIM2 inflammasome in microglia." (PMID 34156153, 2021). "Given that HDAC3 inhibition has been shown to be neuroprotection for ischemic stroke with non-delactylase functions 44-47, suggesting that there may exist complex regulative mechanisms that deserve further deep investigation." (PMID 39113798, 2024). "Unlike reports indicating that HDAC3 directly mediates p65, our findings suggest that Nrf1 acetylation may serve as a link between HDAC3 and p65 interaction in microglia following ischaemic stroke." (PMID 39198723, 2024). "We found that PTS decreased HDAC3 expression and activity, increased Nrf1 acetylation in the cell nucleus and inhibited the interaction of Nrf1 with p65 and p65 accumulation, which reduced infarct volume and neuroinflammation (iNOS/Arg1, TNF-α and IL-1β levels) after ischaemic stroke." (PMID 39198723, 2024).
Alzheimer disease (10 papers, 2015 to 2025). A progressive, neurodegenerative disease characterized by loss of function and death of nerve cells in several areas of the brain leading to loss of cognitive function such as memory and language. "The authors demonstrated that voluntary running wheel over eight weeks improved cognitive performance by downregulating Hdac3, and this process was linked to improved long-term memory and the recovery of contextual memory deficits in an Alzheimer’s disease (AD) mice model." (PMID 39596111, 2024). "In an APP/PS1 transgenic mouse model of Alzheimer's disease, inhibition of HDAC3 in the hippocampus alleviated microglial activation, which showed therapeutic potential for Alzheimer's disease." (PMID 34512154, 2021). "HDAC3, in particular, is an interesting target in Alzheimer’s disease, since it is reported that HDAC3 plays an important role in maintaining long-term memory for object location." (PMID 29498635, 2018). "For Alzheimer's disease, preliminary evidences demonstrated inhibition of HDAC3 enzyme in neurons prevented amyloid-beta oligomer-induced synaptic plasticity impairments and enhanced memory process." (PMID 28293439, 2017).
Cerebral ischemia (10 papers, 2015 to 2025). Restriction of arterial blood supply to the brain associated with insufficient oxygenation to support the metabolic requirements of the tissue. "It has been reported that HDAC3 is up-regulated in various pathological states of the central nervous system, such as cerebral ischemia, craniocerebral trauma, and subarachnoid hemorrhage, and it has been proven to impart neurotoxic effects." (PMID 40584448, 2025). "For example, miR-193b-3p can alleviate focal cerebral ischemia and reperfusion injury in rats, regulate cartilage formation and chondrocyte metabolism by targeting HDAC3, and regulate hepatocyte apoptosis in selenium-deficient broilers by targeting MAML1." (PMID 37078747, 2023). "The current data showed the elevation of DNMT1 and HDAC3 in cerebral ischemia corresponding with the changes in the previous studies." (PMID 39281061, 2022). "The suppression of HDAC3 can improve oxidative stress imbalance and brain damage in cerebral ischemia." (PMID 39281061, 2022). "We aimed to explore the role and the potential mechanisms of HDAC3 in cerebral ischemia/reperfusion (I/R) injury in diabetic state." (PMID 30906786, 2019). "Several cleavages of HDAC3 by different proteases, which are activated with temporal specificity in the process of cerebral ischemia, are involved in regulating the cellular distribution of HDAC3." (PMID 27965534, 2016). "RGFP966, a highly selective HDAC3 inhibitor, has demonstrated neuroinhibitory and neuroprotective impacts in several central nervous system diseases, encompassing neurodegenerative diseases, cerebral ischemia and spinal cord injury." (PMID 38708192, 2024). "In this light, pan-inhibition of histone deacetylase (HDAC) activity is efficacious in animal models of cerebral ischemia and specific knockdown of HDAC3 or HDAC6 promotes survival of cortical neurons in an in vitro model of ischemia employing oxygen and glucose deprivation." (PMID 26541514, 2015). "Other studies have reported similar findings in experimental cerebral ischemia models with the use of RGFP966, a histone deacetylase 3 inhibitor, and gonadal steroid hormones progesterone and 17β-estradiol." (PMID 37765019, 2023). "In another study, HDAC3 expression was elevated in microglia after cerebral ischemia in mice but not in neurons or astrocytes." (PMID 40584448, 2025). "Moreover, histone deacetylase 3 (HDAC3) activates the cGAS-STING pathway and the deletion of cGAS or HDAC3 in microglia attenuates cerebral ischemia/reperfusion-induced neuroinflammation and brain injury." (PMID 35456028, 2022).